YAP1 (Yes1 associated transcriptional regulator)
Diseases named in the same sentence as YAP1 in open-access papers (continued):
Sharing a sentence is not in itself a finding about the gene and the disease.
gastric cancer (continued). "METTL3 induced proliferation, migration, angiogenesis and tumorigenesis via inhibition of ADAMTS9 and modification of YAP1 and KLF2 in gastric cancer." (PMID 36003776, 2022). "In turn, the overexpression of YAP1 eliminates the inhibitory effect of METTL3 silencing on the proliferation, migration, and invasion of gastric cancer cells." (PMID 34394353, 2021). "In summary, the present study found the pro-tumorigenic effect of CLDN6 in gastric cancer and revealed that CLDN6 promoted YAP1 nuclear translocation by reducing YAP1 phosphorylation, thereby activating downstream oncogenes." (PMID 31827075, 2019). "The up‐regulation of YAP1 can promote RAF/MEK/ERK pathway activities and thus enhance the expression of c‐FOS in gastric cancer cells." (PMID 28782275, 2018). "However, in gastric cancer, USP49 stabilizes YAP1 through deubiquitination, and YAP1 in turn promotes the transcription of USP49, forming a positive feedback loop that drives the malignant progression of gastric cancer." (PMID 40607251, 2025). "In summary, our study uncovered that NAT10-mediated ac4C modification stabilizes lncRNA XIST, which recruits hnRNPK to facilitate YAP1 nuclear translocation and transcriptional activation, thereby driving VEGFA-dependent vascular abnormalization in gastric cancer." (PMID 40860183, 2025). "Collectively, our analysis of transcriptomics data from human gastric cancer patients and data from our in vivo gastric cancer model demonstrate the concomitant elevation of YAP1 and receptor components of the gp130/STAT3 signalling pathway during gastric cancer development." (PMID 37957015, 2024). "In lung cancer cells, COPB2 inhibits apoptosis and promotes cell proliferation and tumorigenesis through up-regulation of YAP1 expression, while COPB2 knockdown in gastric cancer cells suppresses cell proliferation and promotes apoptosis by repressing the RTK signaling cascade." (PMID 31926110, 2020). "We then assessed the interaction of AGK and Hippo‐YAP1 pathway in gastric cancer cells and found that AGK overexpression was able to up‐regulate level of YAP1 and CTGF proteins, but lead to a down‐regulation of the level of LATS1/2 and p‐YAP without changing in MST1/2 levels." (PMID 32827244, 2020). "Additionally, the expression of YAP1, FOXM1, KRAS, and BATF genes were decreased in gastric cancer cells by treatment of UA." (PMID 31547587, 2019). "However, the role of YAP1 in gastric cancer (GC) is still in dispute." (PMID 29113304, 2017). "In MKN28 and AGS cell lines, western blot assay showed that p-LATS and p-YAP1 levels were increased significantly in the sh-CLDN6 group.The increased levels of p-YAP1 led to decreased YAP1 entry into the nucleus, thereby inhibiting the development of gastric cancer." (PMID 31827075, 2019). "In addition, this study further found that the inhibition of the expression of the YAP1 signaling pathway by peptide 17 in vitro and nude mice tumor formation models also eliminated the promoting effect of METTL3 on the proliferation and metastasis of gastric cancer cells." (PMID 34394353, 2021). "By establishing two HER2 positive gastric cancer cell lines that was stably resistant to trastuzumab and by establishing two animal models, we determined that upregulated HER4 proteins interacted with YAP1 to induce EMT could subsequently stimulate cancer cell metastasis." (PMID 29535422, 2018). "Although YAP1 has already been identified as a substrate of OTUB1 in the regulation of stemness and progression of gastric cancer cells, there have been no reports on the regulation of YAP1 by OTUB1 in HNSCC to date." (PMID 37986681, 2023). "The expression of YAP1 was not significantly correlated with OS and DFS in breast, colorectal, and gastric cancers." (PMID 34150844, 2021).
hepatocellular carcinoma (124 papers, 2007 to 2025). A malignant tumor that arises from hepatocytes. "Although Yes-associated protein 1 (YAP1) is an important oncogene in hepatocellular carcinoma (HCC) progression, its nuclear localization prevents it from being considered a potential therapeutic target." (PMID 40191726, 2025). "A recent study showed that elevated level of ROS in hepatocellular carcinoma increased the expression of the Yes-associated protein 1 (YAP1), the effective transcription factors of the Hippo pathway." (PMID 36831193, 2023). "For instance, in liver tumors (hepatocellular carcinoma and cholangiocarcinoma) YAP1 cytoplasmic expression was associated with keratin 19 expression which was associated with cancer aggressiveness and patients' poor prognosis." (PMID 29850494, 2018). "In this study, we aimed to assess the role of the Hippo pathway in hepatic carcinogenesis and morphogenesis by examining Yes-associated protein 1 (YAP1) expression in the spectrum of hepatic carcinomas based on cellular lineage." (PMID 28645247, 2017). "YAP1 has been associated with poor prognosis in gastric cancer, gallbladder cancer, and hepatocellular carcinoma." (PMID 28645247, 2017). "Both in vivo and in vitro experiments confirmed that MKLN1 may promote the development of hepatocellular carcinoma by affecting yes1-associated transcriptional regulator (YAP1)." (PMID 38139458, 2023). "Moreover, menin, the protein product encoded by MEN1, can modulate the expression of YAP1: In human hepatocellular carcinomas menin epigenetically upregulates YAP1 gene expression." (PMID 33670622, 2021). "Enhanced secretion of IL-6 by YAP1-activated hepatocellular carcinoma cells might induce tumor-associated macrophage maturation, and disruption of YAP1 function could suppress macrophage chemotaxis and migration." (PMID 33057010, 2020). "Although we could identify an association between poor prognosis and activated YAP1 in hepatic carcinomas, this was only confirmed in the pT1 stage IHCCA patients." (PMID 28645247, 2017). "Similarly, mouse Mst1/2 deficiency in the liver results in the loss of inhibition of Yap1, massive liver overgrowth and hepatocellular carcinoma formation." (PMID 24489653, 2014). "Zhou and colleagues established that combined Mst1/Mst2 deficiency in the liver results in massive overgrowth and hepatocellular carcinoma as the loss of Mst1/Mst2 signaling abrogates Yap1 phosphorylation, leading to enhanced Yap1 activity in the nucleus and an increased transcriptional activity." (PMID 22363786, 2012). "The expression of miR-186 is reduced in hepatocellular carcinoma (HCC), and it can inhibit the occurrence and development of HCC by targeting yes-associated protein 1 (YAP1)." (PMID 35308517, 2022). "IQGAP1 mRNA/protein levels are upregulated in hepatocellular carcinoma (HCC), a cancer type where loss of the core proteins of the Hippo pathway and upregulation of YAP1 proliferative signal have been shown to result in cancer development." (PMID 33672268, 2021). "According to the research in hepatocellular carcinoma, matrix stiffness boosts the stem-like phenotype of tumor cells by YAP1." (PMID 40822927, 2025). "Studies have shown that the long non-coding RNA lnc-CTHCC binds to hnRNP K and activates YAP1 transcription, thereby promoting the development of hepatocellular carcinoma." (PMID 41285764, 2025). "Hepatocellular carcinoma (HCC) is one of the most lethal malignancies, frequently characterized by high expression and activation of Yes-associated protein 1 (YAP1), a key effector in the Hippo signaling pathway." (PMID 40307228, 2025). "For instance, SETD1A, a histone H3K4 methyltransferase, has been shown to transcriptionally activate YAP1, thereby promoting primary resistance to sorafenib in hepatocellular carcinoma." (PMID 40977060, 2025). "Dihydroartemisinin(DHA) reduces lipid droplet accumulation in hepatocellular carcinoma by inhibiting YAP1 and enhances sensitivity to PD-1 therapy." (PMID 40028341, 2025).
hepatocellular carcinoma (continued). "In lung, prostate, and hepatocellular cancer, researchers found that UBTD1 is found to catalyze Yes1-associated transcriptional regulator (YAP) protein degradation and inhibit the development of lung, prostate, and hepatocellular cancer." (PMID 39003255, 2024). "Since YAP1 plays a pro-proliferative function in epithelial cells, the latter event promoted the onset of hepatocellular carcinoma (HCC)." (PMID 38812048, 2024). "Recently, it has been reported that lnc-CTHCC binds to transcription factor heterogeneous nuclear RNP K and activates YAP1 transcription and promotes progression of hepatocellular carcinoma." (PMID 37257820, 2023). "Another study showed that circGPRC5A can bind miR-1283 and activate the YAP1/TEAD1 signaling pathway to promote the growth of hepatocellular carcinoma." (PMID 38057879, 2023). "In liver carcinoma, YAP1 promoted the infiltration of macrophages by upregulating the expression of monocyte chemoattractant protein-1." (PMID 37752152, 2023). "Studies have reported that YAP1 promotes tumorigenesis and progression in hepatocellular carcinoma by upregulating Jagged 1 and activating the Notch pathway." (PMID 38505381, 2023). "Specifically, restoring the level of YAP1 significantly inhibits proliferation and increases chemosensitivity of hepatic carcinoma cells." (PMID 35656547, 2022). "Overexpressed microRNA-186 inhibits cell proliferation and migration by downregulating YAP1 in hepatocellular carcinoma." (PMID 34082774, 2021). "It has been shown that YAP1 and TAZ bind directly to the SLC7A5 promoter to upregulate its transcription and inhibition of SLC7A5 blocks YAP1/TAZ-mediated tumorigenesis of hepatocellular carcinoma." (PMID 33953707, 2021). "In hepatocellular carcinoma, LATS2 mediated yes-associated protein (YAP) phosphorylation and promoted nuclear localization of YAP1 and YAP1/TEAD2 interactions, which in turn induced cancer progression." (PMID 34699318, 2021). "Loss of HNF4A expression in a chronic setting can further stem from induction of the oncoprotein gankyrin which enhances proteasome-dependent HNF4A degradation in hepatoma cells and the persistent YAP1 activation in HCC." (PMID 32998360, 2020). "In hepatocellular carcinoma, previous study proved that YAP1/TAZ activated the mTORC1 pathway via up- regulating amino acid transporters (SLC38A1 and SLC7A5) to promote cell growth." (PMID 32003757, 2020). "A recent study demonstrated that circ-104075 stimulated YAP1 expression via absorbing miR-582-3p, therefore to stimulate hepatocellular carcinoma tumorigenesis." (PMID 32541093, 2020). "miR-186-5p acts similarly to upregulate yes-associated protein 1 (YAP1) expression, thus promoting the tumorigenesis of hepatocellular carcinoma." (PMID 32117705, 2020). "Recently, a report demonstrated that UHMK1 expression was drived by an oncogene called yes-associated protein 1 (YAP1), a key factor in Hippo signaling pathway, through a combination effect of FOXM1 in hepatoma." (PMID 32580279, 2020). "A recent study showed that YAP1 is amplified in a vast array of solid tumors, including brain, colon and hepatocellular carcinomas, and it has been consistently reported as an oncogene in epithelial cancers." (PMID 29728107, 2018). "Our study tried to elucidate the role of the Hippo pathway in the morphogenesis of the liver in regards to liver carcinomas and found that YAP1 activation was more commonly found in CCAs than pure HCCs." (PMID 28645247, 2017).
hepatocellular carcinoma (continued). "Overexpression of YAP1 has been reported in the early phase of hepatocellular carcinomas, but the induction of hepatoblastoma required coactivation of β-catenin and interaction with PI3K has been reported to be involved in the induction of CCAs." (PMID 28645247, 2017). "In cervical cancer and hepatocellular carcinoma, YAP1 can activate EGFR signaling by upregulating the expression of TGF-α or AREG." (PMID 29228705, 2017). "Ruan T reported that miR-186 targets YAP1 to inhibit Hippo signaling and tumorigenesis in hepatocellular carcinoma." (PMID 28915618, 2017). "YAP1 amplification has been described as an essential oncogene in a large number of human cancers, including gesophageal squamous cell carcinomas, hepatocellular carcinomas, non-small cell lung cancer, prostate cancer, ovarian cancer and CRC." (PMID 25473897, 2015). "YAP1 might also drive c-Myc transcription through interaction with c-Abl, and thereby, enhance hepatoma cell growth, while the role of c-Myc in the development of autophagy-deficient hepatoma cells was not studied in this investigation." (PMID 35321438, 2022). "In addition, circGprc5a contributes to hepatocellular carcinoma progression by binding with miR-1283 to activate the YAP1/TEAD1 signaling pathway." (PMID 35415250, 2022). "Previous studies showed that YAP1 is over-expressed in hepatocellular carcinoma (HCC)." (PMID 27359056, 2016). "Moreover, YAP1 was determined to be an independent prognostic marker for overall survival of hepatocellular carcinoma and esophageal squamous cell carcinomas." (PMID 24621512, 2014). "The relevance of this phenomenon in cancer has been shown for the genes MMP13, Birch2, and Birch3, which are functionally related oncogenes contained on the same amplification in osteosarcoma, and for BIRC2 and YAP1, cooperating oncogenes in an amplification in hepatocellular carcinomas." (PMID 23393560, 2013). "E3 ubiquitin ligases, such as the F‐box and WD40 repeat domain containing‐7 (Fbxw7) and β‐TrCP destabilize YAP1 by targeting it for ubiquitination and proteasomal degradation in hepatocellular carcinoma (HCC) and pancreatic cancer." (PMID 39968498, 2025). "Incidentally, it has been reported that YAP1 can negatively regulate HNF4α expression through ubiquitination and proteasomal degradation in hepatocellular carcinoma (HCC) cells." (PMID 34693980, 2021). "Further, YAP1 also reprograms hepatocyte glutamine metabolism for liver regeneration and has been shown to promote hepatocellular carcinoma (HCC) cell growth and migration." (PMID 31695785, 2019). "Moreover, YAP1 increased the iron concentration in hepatocellular carcinoma cells (HCC) through transcriptional elevation of TfR1 via its O-GlcNAcylation." (PMID 39917623, 2025). "In contrast, YAP1 and WWTR1 gene fusions have so far been undetected in some common tumors with prevalent YAP and TAZ activation, such as hepatocellular carcinoma." (PMID 40491864, 2024). "FGF21 promotes ferroptosis in hepatocellular carcinoma by upregulating Major vault protein (MVP), which enhances NOX4-mediated ROS production through IRF1 and YAP1 interactions." (PMID 39315094, 2024). "Disruption of the HIPPO kinase module is common in several cancers, including hepatocellular carcinoma (HCC) and Mesothelioma, amongst others, resulting in nuclear accumulation of YAP1 and TAZ." (PMID 38939918, 2024). "NUP37 is a major component of the nuclear pore complex, which regulates the stability of YAP1 in a LRP5-dependent manner and promotes the progression of hepatocellular carcinoma." (PMID 38304253, 2023). "NUAK2 was shown to be required for tumourigenesis in a YAP1‐driven model of hepatocellular carcinoma, while a dual‐specific NUAK inhibitor suppressed growth of YAP1 overexpressing tumour xenografts." (PMID 36975767, 2023).
hepatocellular carcinoma (continued). "CircCPSF6, which was upregulated in hepatocellular carcinoma specimens, competitively interacted with PCBP2 to inhibit its binding to YAP1 mRNA, thus attenuating PCBP2-mediated destabilization of YAP1." (PMID 35701841, 2022). "In hepatoma cells, the S1P/S1PR2/YAP1 signaling axis stimulates cell proliferation by upregulating connective tissue growth factor." (PMID 36498853, 2022). "Further evidence for the positive regulation of YAP1 by PI3K signaling was reported in mammary tumorigenesis and hepatocellular carcinoma." (PMID 35459264, 2022). "In esophageal cancer, YAP1 was found to mediate EGFR overexpression, while a reciprocal relationship was found in hepatocellular carcinoma, where EGFR induced expression of YAP1." (PMID 34944063, 2021). "The level of YAP1 protein is elevated a variety of cancers, including colorectal cancer (CRC), gastric cancer, esophageal squamous cell cancer (ESCC), human hepatocellular carcinoma (HCC), osteosarcoma." (PMID 34953494, 2021). "In hepatocellular carcinoma (HCC), YAP1 cooperates with forkhead box M1 to drive chromosomal instability-related gene expression." (PMID 31175271, 2019). "However, the heterogeneous pattern of YAP1 expression between cHC-CCAs and CK19(+) HCCs and the poor prognosis of YAP1 positive hepatic carcinomas suggests that YAP1 may have a preferential role in aggressive tumor behavior, rather than in the determination of cellular lineage in hepatic carcinomas." (PMID 28645247, 2017). "We analyzed the promoter methylation of members of the Hippo pathway in hepatocellular cancer and observed tumor-specific hypermethylation of RASSF1A, although YAP1 was unmethylated." (PMID 29179447, 2017). "The interplay between YAP1 and EGFR signaling was noted previously where EGFR activation induced YAP1 gene expression in a study of hepatocellular carcinoma, while YAP1 induced EGFR expression in another report." (PMID 26716514, 2016). "Furthermore, YAP1 (located on 11q22) has been identified as a candidate oncogene in several cancers; its overexpression and increased nuclear localization have been reported in breast cancer, hepatocellular carcinoma, colorectal cancer, GC, pancreatic cancer, and esophageal squamous cell carcinoma." (PMID 27835600, 2016). "In a clinical study, the selective colocalization of β-catenin and YAP1 in the nucleus was identified in approximately 80% of hepatocellular carcinoma patients but not in patients with hepatocellular carcinoma or cholangiocarcinoma." (PMID 40438141, 2025). "In hepatocellular carcinoma, miR-21-3p regulates both TGFβ and Hippo signalling via SMAD7 and YAP1." (PMID 38920689, 2024). "In hepatocellular carcinoma (HCC), CBX4 has been reported to induce nuclear translocation of YAP1 protein and regulated tumorigenicity and stem-like properties of HCC cells." (PMID 40861818, 2025). "Here, we demonstrate that YAP1 and IL6ST are novel substrates of chaperone-mediated autophagy (CMA) in human hepatocellular carcinoma (HCC) and hepatocyte cell lines." (PMID 35435804, 2023). "Current studies suggest that upregulation of STMN1 can accelerate the formation and/or progression of hepatocellular carcinoma by activating the YAP1 signaling pathway, and overexpression of STMN1 may be a precursor of hepatocellular carcinoma and can be used as a marker for diagnosis and treatment." (PMID 36127700, 2022). "Consistently, expression of YAP1/TAZ downstream genes was significantly increased in the liver of Atg7ΔHepFgf21−/− mice compared to Atg7ΔHepFgf21+/+ mice, which could explain the increased size of hepatoma in Atg7ΔHepFgf21−/− mice." (PMID 35321438, 2022). "The reciprocal regulation of tumor-initiating stem-like cells by TLR4, and TGF-β requires YAP1 and IGF2BP3 in hepatocellular carcinoma (HCC)." (PMID 29312609, 2017).